CADPS2 (calcium dependent secretion activator 2)
Description:
Calcium-binding protein involved in exocytosis of vesicles filled with neurotransmitters and neuropeptides. Probably acts upstream of fusion in the biogenesis or maintenance of mature secretory vesicles. Regulates neurotrophin release from granule cells leading to regulate cell differentiation and survival during cerebellar development. May specifically mediate the Ca(2+)-dependent exocytosis of large dense-core vesicles (DCVs) and other dense-core vesicles (By similarity).
Synonyms: CAPS2
Tractability: Antibody: UniProt places it where antibodies can reach, with high confidence. PROTAC: its protein half-life has been measured.
Gene: Protein-coding gene on chromosome 7 (122,318,411 to 122,886,779, reverse strand). Ensembl gene ENSG00000081803.
Subcellular location: Cytoplasmic vesicle membrane; Synapse; Cell projection, cilium; Cytoplasm, cytoskeleton, cilium basal body; Cytoplasm, cytoskeleton, microtubule organizing center, centrosome
Subcellular location (Human Protein Atlas): Nucleoplasm; Vesicles
Gene Ontology:
Biological process: exocytosis; positive regulation of exocytosis; dense core granule exocytosis; synaptic vesicle exocytosis; synaptic vesicle priming
Cellular component: centrosome; ciliary basal body; cilium; glutamatergic synapse; cytoplasmic vesicle; cytoplasmic vesicle membrane; parallel fiber to Purkinje cell synapse; postsynaptic membrane; presynapse; presynaptic membrane; synapse
Genetic constraint (gnomAD): Loss-of-function variants: 55 observed, 98.51 expected, observed/expected ratio (o/e) 0.56, 90% interval 0.45 to 0.7. The upper end of that interval is the gene's LOEUF score, 0.7, which puts it in group 2 of 6, group 1 being the genes least tolerant of losing a copy. Missense variants: 1,051 observed, 1,154.3 expected, observed/expected ratio (o/e) 0.91, 90% interval 0.87 to 0.96. Synonymous variants: 407 observed, 408.49 expected, observed/expected ratio (o/e) 1, 90% interval 0.92 to 1.08.
Homologues: Orthologues: chimpanzee CADPS2 (99% identical), macaque CADPS2 (99% identical), rat Cadps2 (96% identical), pig CADPS2 (96% identical), rabbit CADPS2 (94% identical), mouse Cadps2 (93% identical), guinea pig CADPS2 (86% identical), dog CADPS2 (85% identical), tropical clawed frog cadps2 (83% identical), Drosophila melanogaster Cadps (60% identical), Caenorhabditis elegans unc-31 (49% identical), zebrafish cadps2 (23% identical).
Diseases named in the same sentence as CADPS2 in open-access papers:
CADPS2 is named in the same sentence as 26 diseases in open-access papers, as found by Europe PMC text mining. Sharing a sentence is not in itself a finding about the gene and the disease. The quoted sentences say what the papers report.
autism (12 papers, 2011 to 2023). Persistent deficits in social interaction and communication and interaction as well as a markedly restricted repertoire of activity and interest as well as repetitive patterns of behavior. "CADPS2 is located in the “autism susceptibility locus 1” on chromosome 7q31.3249 and genetic variants have been associated with autism spectrum disorders and intellectual disability." (PMID 36086934, 2022). "CADPS2, the gene disrupted by the translocation in family 2, maps within the autism susceptibility locus 1 on 7q31-q33 and has been linked in a number of studies with ID and autism." (PMID 28072833, 2017). "In this context, several genes downregulated in the brainstem of Hoxa5 cKO mouse at P21, such as Grm4, Cbln1, En2, Camk4, and Cadps2, have been associated to autism traits either in humans or in mouse models." (PMID 29187810, 2017). "CADPS2, located at the autism-susceptibility locus on chromosome 7q31, is abnormally spliced in autism patients, and Cadps2−/− mice exhibit social interaction deficits, including maternal neglect." (PMID 23935565, 2013). "The human homolog of Cadps2 has been linked to autism and lies in the 7q autism susceptibility locus (AUTS1)." (PMID 21253556, 2011). "Mutations of AUTS2 (and also in gene CADPS2) are implicated in autism." (PMID 34073168, 2021). "CADPS2, located in a region previously referred to as autism susceptibility locus 1 (AUTS1) (International Molecular Genetic Study of Autism Consortium, 2001)." (PMID 36479251, 2022). "Cadps2 was a DOT1L-dependent gene and its expression levels need to be tightly controlled, as imbalanced levels are associated with neurological diseases such as autism." (PMID 30302725, 2019). "Thirty-six Italian patients with ID and 187 probands with ASD [of which 94 from Italy and 93 from the International Molecular Genetic Study of Autism Consortium (IMGSAC) collection] were recruited for mutation screening of all exon and exon–intron boundaries of the CADPS2 gene (NM_017954.10)." (PMID 24737869, 2014).
autism spectrum disorder (9 papers, 2013 to 2024). A spectrum of developmental disorders that includes autism, and Asperger syndrome. "In this context, we previously reported that up-regulation of the Autism Spectrum Disorder-associated gene CADPS2, and other neurodevelopmental disorder-related genes (BACE2 and DSCR5) were detected in GS macaques." (PMID 27801835, 2016). "Duplications of this gene are not reported in the literature, but duplication of CADPS2, a member of the same gene family, was reported in autism spectrum disorders." (PMID 38178910, 2023).
depression (3 papers, 2012 to 2026). "Additionally, there exist a multitude of significant genes that vary between sexes and are linked to depression, like ORM1, ORM2, RNF32, SLC25A5, Thbs1, and Cadps2 etc., manifesting sex-specific impacts on depression risk." (PMID 38903903, 2024). "In previous SNP level analyses, ERG, NEBL, CADPS2, GABBR2, and HDAC9 genes have been reported to be related with neuropsychiatric diseases such as BD, depression disorder, and schizophrenia." (PMID 22901090, 2012).
epilepsy (2 papers, 2014 to 2017). A brain disorder characterized by episodes of abnormally increased neuronal discharge resulting in transient episodes of sensory or motor neurological dysfunction, or psychic dysfunction. "We identified a novel intragenic deletion of maternal origin in two siblings with mild ID and epilepsy in the CADPS2 gene, encoding for a synaptic protein involved in neurotrophin release and interaction with dopamine receptor type 2 (D2DR)." (PMID 24737869, 2014). "Using qRT–PCR, we validated the downregulation of ASD-related genes involved in cerebellar development (Cadps2 and Reln) (refs 28, 43), and ASD- or epilepsy-related ion channels in neurons (Cacna2d1, Grik2 and Kcnd2) (refs 43, 44, 45) in ICRF-193 treated or Chd7 mutant CGNs." (PMID 28317875, 2017).
neuroblastoma (2 papers, 2014 to 2022). Neuroblastoma (NB) is the most common solid, extracranial childhood tumor. "The same study evaluated CADPS2 promoter‐dependent transcriptional activity in human neuroblastoma SK‐N‐SH cells overexpressing WT or the PD‐causing SNCA A30P mutation." (PMID 36086934, 2022).
Parkinson disease (2 papers, 2020 to 2022). A progressive degenerative disorder of the central nervous system characterized by loss of dopamine producing neurons in the substantia nigra and the presence of Lewy bodies in the substantia nigra and locus coeruleus. "Moreover, additional in vitro and in vivo experiments are necessary to explore the role of CADPS2 in the pathogenesis of Parkinson’s disease and to elucidate how the observed glial interplay perpetuates or induces DaN demise." (PMID 34919646, 2022). "The predisposition genes potentially linked to the neurological form of CD were identified by messenger-RNA (mRNA) profiling: CADPS2 (ASD), CAPN13 (AD), BACE2 (AD, DS), DSCR5 (DS), and PINK1 (Parkinson’s Disease (PD)." (PMID 32751379, 2020).
acinar cell carcinoma (1 paper, 2022). "The filamentous granules in Cadps2 KO acinar cells correspond well to those which are generally known to be a characteristic of acinar cell carcinomas; both categories of granules display variously-elongated shapes and rich filaments bound in limiting membrane." (PMID 36419930, 2022).
chondrodysplasia (1 paper, 2025). "CADPS2 was associated with the occurrence of chondrodysplasia in Texel sheep." (PMID 40965274, 2025).
chronic pancreatitis (1 paper, 2022). A chronic inflammatory process causing damage and fibrosis of the pancreatic parenchyma. "We used whole exosome sequencing to identify CADPS2 variants in patients with chronic pancreatitis (CP)." (PMID 36419930, 2022). "Finally, we analyzed variations of CADPS2 in patients with chronic pancreatitis (CP) via whole exosome sequencing." (PMID 36419930, 2022).
mental disorder (1 paper, 2023). A disease that has its basis in the disruption of mental process. "Finally, the mature stage T5 was enriched for synaptic signaling genes (FDR = 5 × 10–16; e.g., CADPS2 and SNAP25) and regulation of membrane potential (FDR = 3 × 10–11; e.g., RIMS1 and SCN2A), and was most specifically marked by RBFOX1, an RNA-binding protein implicated in many mental disorders." (PMID 36865235, 2023).
schizophrenia (1 paper, 2012). A major psychotic disorder characterized by abnormalities in the perception or expression of reality. "A significant increase in CADPS2 expression was detected in the brains of the schizophrenia group, compared to the control group." (PMID 22901090, 2012). "The remained CADPS2, GABBR2, and DHAC9 genes are related with schizophrenia." (PMID 22901090, 2012).
neurodevelopmental disorder (2 papers, 2014 to 2016). A behavioral and cognitive disorder with onset during the developmental period that involves impaired or aberrant development of intellectual, motor, or social functions. "Therefore, it is essential to reinterpret the available data on CADPS2 variants (both sequence and copy number) gathered in other studies in light of parent-of-origin effect, in order to validate the role of CADPS2 in neurodevelopmental disorders." (PMID 24737869, 2014).
cancer (1 paper, 2016). A tumor composed of atypical neoplastic, often pleomorphic cells that invade other tissues. "‘Cancer’ was the most represented function, with 57 genes, including BDNF, NR2C2 and CADPS2 (1.99 × 10–8 < P < 1.23 × 10–2)." (PMID 26999292, 2016).
neurodegenerative disease (1 paper, 2022). A disorder of the central nervous system characterized by gradual and progressive loss of neural tissue and neurologic function. "In this study we report three parrot siblings with a rapidly progressive neurodegenerative disease which we propose is caused by a spontaneous homozygous missense mutation (c.1675G > C; p.V559L) in the CADPS2 gene." (PMID 36086934, 2022). "Although CADPS2 variants have not been reported to cause neurodegenerative diseases in humans, further investigation of the gene in animal models might provide important insights into the pathophysiology of LB disorders." (PMID 36086934, 2022). "Taken together, these data suggest that CADPS2 regulates presynaptic BDNF release in dopaminergic neurons, which is particularly relevant to PD and other neurodegenerative diseases." (PMID 36086934, 2022).
tumor (1 paper, 2023). "Recently, ACT of T-cells targeting mutant proteins (SLC3A2, KIAA0368, CADPS2 and CTSB) detected in a patient tumor in combination with interleukin two have been demonstrated to induce tumor regression." (PMID 36910138, 2023).
CADPS2 also shares sentences with these, for which no sentence is quoted: Intellectual disability (2 papers); acute pancreatitis (1); alcoholic (1); cerebellar ataxia (1); diabetes (1); eye disorder (1); glioma (1); metabolic syndrome (1); neurological diseases (1); pancreatitis (1); prostate carcinoma (1).